RNU6ATAC (RNA, U6atac small nuclear)
Synonyms: RNU6ATAC1; MEJINS; U6ATAC
Gene: Small nuclear RNA gene on chromosome 9 (134,164,439 to 134,164,564, reverse strand). Ensembl gene ENSG00000221676.
Gene Ontology:
Molecular function: pre-mRNA 5'-splice site binding; U4atac snRNA binding
Biological process: mRNA 5'-splice site recognition; spliceosomal tri-snRNP complex assembly
Cellular component: U6atac snRNP
Homologues: Orthologues: chimpanzee RNU6ATAC (100% identical), macaque RNU6ATAC (100% identical), dog RNU6ATAC (98% identical). Paralogues in human: RNU6ATAC6P (90% identical), RNU6ATAC7P (89% identical), RNU6ATAC21P (88% identical), RNU6ATAC27P (87% identical), RNU6ATAC41P (87% identical), RNU6ATAC8P (87% identical), RNU6ATAC19P (69% identical), RNU6ATAC39P (60% identical), RNU6ATAC22P (59% identical).